IL1B (interleukin 1 beta)
Diseases named in the same sentence as IL1B in open-access papers (continued):
Sharing a sentence is not in itself a finding about the gene and the disease.
colitis (continued). "Additionally, recent findings suggest that glial cells in mice contribute to intestinal inflammation by activating macrophages and polarizing them toward a pro-inflammatory state, which was amplified by proinflammatory IL-1β during a mouse colitis model." (PMID 39149516, 2024). "In addition, black tea inhibited inflammatory cytokines including IL-12, IL-23, IL-6, and IL-1β, and suppressed IκBα phosphorylation and activity of NF-κB in an LPS-induced colitis model." (PMID 39572022, 2024). "Using macrophage-specific AhR-deficient mice, we found that AhR△mye mice developed severe colitis on DSS treatment, characterized by a significant increase in macrophage pyroptosis and subsequent IL-1β release in colon tissues, compared with AhRfl/fl littermates." (PMID 39113799, 2024). "In our study, we found that the colitis model had higher IL-1β levels than normal mice." (PMID 39201260, 2024). "However, we did observe higher expression of key inflammatory cytokines (Il6, Il1b, Il17b) and chemokines (Cxcl1 and Cxcl2) involved in colitis in wild-type compared to R38E-PAR2 mice." (PMID 39171684, 2024). "IL-1β can down-regulate the mRNA level of occludin and increase intestinal TJ permeability, all of which are related to the onset and deterioration of colitis symptoms." (PMID 39452928, 2024). "TNF-α, IL-6, and IL-1β are highly expressed in experimental mice colitis." (PMID 39148547, 2024). "To determine whether IL-1β is required for host defense during infection-induced colitis, we challenged streptomycin-treated WT and IL-1β-/- mice (on a C57BL/6 background; Nramp1sS1 Fig) with a single oral dose of Salmonella." (PMID 38236896, 2024). "Furthermore, it has been shown that the activation of AHR by various endogenous ligands inhibits the NF-κB signaling pathway, reducing the expression of IL-1β and IL-6 in conditions such as periodontitis, bronchitis, and colitis." (PMID 39465158, 2024). "In addition, a reduction in colitis severity was associated with significantly lower colonic MPO and IL-1β levels." (PMID 38713616, 2024). "Administration of IL-1β to NLRP3-null mice has shown protection against oxazolone-induced colitis." (PMID 39769450, 2024). "Inhibition or knockdown of the NLRP3 inflammasome could alleviate the severity of DSS-induced colitis, control the release of IL-1β and IL-18, and suppress the inflammatory response of UC." (PMID 36762118, 2023). "Besides, FMT rescued the elevated inflammatory factors TNF-α, IL-6, and IL-1β in serum and colonic tissue of mice colitis model, indicating that both of CA- and EA-altered microbiota can effectively transfer the colitis protection." (PMID 37813835, 2023). "How IL-1β is affected by C. difficile in colitis needs to be clarified." (PMID 36951545, 2023). "In addition, MCC950, a chemical NLRP3 inhibitor, can significantly suppress the release of the pro-inflammatory cytokines IL-1β, IL-18, and IL-1α in colitis." (PMID 37240022, 2023). "In addition, the TNBS-induced Sprague-Dawley mice model of colitis presented decreased IL-1β, IL-6, IL-12, caspase-1, caspase-3, TXNIP, and NLRP3 levels." (PMID 37367886, 2023). "Besides, although IL-1β is known as the most important inflammatory mediator, IL-1β pre-treated MSCs have shown better efficacy in the treatment of DSS-induced colitis." (PMID 36707899, 2023). "Therefore, we assessed the effects of OPs on inflammation and oxidative stress in mice with colitis by measuring the levels of inflammatory markers (IL-6, IL-1β, TNF-α) and redox markers (MDA, SOD, T-AOC) in serum and colonic tissues." (PMID 38140314, 2023). "In a mice model of colitis, supplementation with penta-O-galloyl-β-D-glucose inhibited colon shortening and myeloperoxidase activity, reduced the activation of NF-κB and levels of IL-1β, TNF-α, and IL-6, but increased IL-10 levels." (PMID 36829984, 2023). "Furthermore, studies have also found that the reduction of IL-1β content in intestinal tissue can improve colitis." (PMID 36899787, 2023).
colitis (continued). "Therefore, we believe the blockade of IL-1β can be used to treat certain types of colitis and warrants further exploration in clinical settings." (PMID 37240022, 2023). "To investigate the effect of BFO on the inflammatory responses of DSS‐induced colitis mice, we determined the mRNA expression levels colon‐related genes, including IL‐1β, IL‐6, TNF‐α, inducible nitric oxide synthase (iNOS), and cyclooxygenase 2 (COX‐2), by qPCR." (PMID 38018589, 2023). "Consistently with the data obtained in murine colitis, Ade/HA determined a significant decrease in the release of IL-1β, TNF-α, IL-6, MPO, and MDA accumulation in cytomix-stimulated tissues, and these effects were accompanied by a significant reduction in the expression of HYAL-1." (PMID 38203336, 2023). "Furthermore, we demonstrated that the blockade of IL-1β ameliorates DSS-induced colitis in VAD mice." (PMID 37240022, 2023). "In addition, in the oxazolone-induced mouse UC model, NLRP3 knockout mice have more severe colitis, as indicated by increased Th2 cytokine expression and decreased production of mature IL-1β and IL-18." (PMID 37370025, 2023). "Indeed, miR-223 suppressed NLRP3 expression, reduced IL-1β production, and thus ameliorated the experimental colitis." (PMID 37681916, 2023). "However, FMT failed to rescue the percentage of weight loss and the mRNA levels of Tnf-α, Il-1β, and Il-6, suggesting that intestinal microbiota is involved in the development of DSS colitis." (PMID 37813835, 2023). "The decreased production of IL-1β leads to a reduction in ROS, NF-κB activation, and apoptosis in the intestinal epithelium, all of which help to repair the intestinal barrier and adjust gut microbiota in juvenile colitis mice." (PMID 37396394, 2023). "It has been shown that mesenchymal stem cells (MSC) primed by IL-1β could alleviate intestinal inflammation in DSS-induced colitis." (PMID 37371485, 2023). "As expected, the expression of IL-1β was markedly upregulated in colon and spleen tissues from mice with colitis compared to the control group, and tissues with high expression of FCNB also showed higher IL-1β expression, suggesting the association between FCNB and IL-1β." (PMID 36932401, 2023). "Herein, we aimed to assess the impact of mAb against IL-1β on DSS-induced colitis in VAD B6 mice." (PMID 37240022, 2023). "These anti-inflammatory effects were corroborated by animal studies, which showed that a daily supplementation of bergamot juice extract in a mice experimental colitis model significantly decreased the IL-1β, NK-kbp65, p-JNK, TNF-α colon levels, and the nitrotyrosine positive staining degree." (PMID 36672947, 2023). "Furthermore, our results demonstrate that the expression of genes related to the pathogenesis and diagnosis of colitis such as Il1β, Lcn2, S100a8 and S100a9 were specifically enhanced in Socs3-deficient neutrophils localized to the colon and spleen." (PMID 37283760, 2023). "Elevated production of inflammatory cytokines, such as TNF-α, IL-1β, and IL-6, could injure gut epithelia cells and exacerbate colitis." (PMID 37324477, 2023). "Recent studies display that intraperitoneally injected MSCs (2 × 106) could diminish colitis development and also decrease serum levels of IL-1β, IL-12, and IL-6 in vivo." (PMID 36707899, 2023). "It is known that TLR8 activation can enhance TNF and IL-1β production, both associated with mucosal inflammation in UC, whereas TLR7 agonists could induce a type I IFN response and prevent experimental colitis in mice." (PMID 37446274, 2023). "The results revealed that L. plantarum, COS, and the synbiotics alleviated the symptoms of mice colitis and inhibited the changes in short-chain fatty acids (SCFAs), tumor necrosis factor-α (TNF-α), interleukin (IL)-1β, IL-6, IL-10, and myeloperoxidase (MPO) caused by DSS." (PMID 37297494, 2023).
colitis (continued). "Oral NPs-PEG-FA/6-shogaol can downregulate the proinflammatory factors (TNF-α, IL-6, IL-1β and iNOS), upregulate the expression level of anti-inflammatory factors (Nrf-2 and HO-1), alleviate the colitis symptoms and accelerate the wound repair of DSS-induced colitis mice." (PMID 37033644, 2023). "However, the inosine intervention at 100 mg/kg only significantly reduced the colonic level of IL-1β in mice with colitis (p < 0.01)." (PMID 37762155, 2023). "Therefore, we measured the proinflammatory cytokine production in colon tissues that DSS-induced acute colitis is accompanied by increased cytokine expression shown by ELISA and qRT-PCR, including IL-6, IL-1β and IL-17." (PMID 37143672, 2023). "Possible mechanisms by which DCA affects immunity in DSS-induced murine colitis include increasing IL-1β secretion, reducing the number of tuft cells in the mucosa, and activating CD4+ and CD3+ T cells to exaggerate immune responses, consequently worsening intestinal inflammation." (PMID 36819995, 2023). "The colon’s TNF-α, IL-6, and IL-1β expressions were raised in experimental colitis." (PMID 37646040, 2023). "Enhanced IL1β mRNA expression was shown in the colonic muscle of rats with colitis." (PMID 36982878, 2023). "For instance, Lactobacillus rhamnosus GG could prevent colitis relapse in antibiotic treated rat by downregulating IL-1β production." (PMID 37400621, 2023). "In a dextran sodium sulfate (DSS)-induced murine colitis model, mice with oral stigmasterol administration had a delayed onset of colitis, a reduced pathohistological score in the colon; and a downregulated expression of inflammatory factors, including IL-6, IL-1β, and TNF-α." (PMID 37685017, 2023). "Additionally, IL-1β concentration in DSS-induced mice with colitis was significantly reduced by S. cerevisiae QHNLD8L1 (p < 0.05), and IL-10 concentrations were significantly increased by S. boulardii CNCMI-745 and S. cerevisiae QHNLD8L1 (p < 0.05)." (PMID 37047694, 2023). "Seven hub genes IL10, IL4, IL6, IFNG, IL1B, TNF and IL17A might be responsible for causing Colitis and Arthritis, except for Rheumatoid Arthritis." (PMID 36989283, 2023). "We next speculated whether the increased IL-1β level in the colonic LP and the consequent colitis exacerbation observed in VAD mice are dependent on canonical or non-canonical inflammasome signaling." (PMID 37240022, 2023). "However, it is still unclear if Blautia is effective for treating colitis because it helps to enhance the creation of SCFAs, while is concentrated in UC patients’ gut and positively correlates with IL-1β, IL-6, and TNF-α." (PMID 37297494, 2023). "In a murine model of colitis, the previous and during-induction administration of CC-AST relieves colitis and significantly inhibits the expression of the inflammatory markers IL-1β, IL-6, TNF-α, cyclooxygenase-2, myeloperoxidase (MPO), iNOS, and NO in a more potent way than free AST." (PMID 37514016, 2023). "According to a study in 2018, curcumin could alleviate DSS-induced colitis in mice via the inhibition of the NLRP3 inflammasome with a reduction in IL-1β and IL-6." (PMID 37833958, 2023). "Furthermore, WT mice that received DSS and mtDNA injections had increased severe colitis and high levels of IL-1β." (PMID 36499214, 2022). "Previous studies have shown that the levels of TNF-α and IL-1β decreased in the NLRP3−/−mice with colitis, indicating that NLRP3 could regulate the release of inflammatory cytokines." (PMID 35745163, 2022). "In line with previous studies showing a role for NLRP3 inflammasome in DSS colitis etiopathogenesis, we found an increased expression of both IL1B mRNA and inflammasome components, as well as protein levels of pro-Caspase-1, in colonic tissue of DSS-treated mice." (PMID 35327334, 2022).
colitis (continued). "The results showed that exogenous ghrelin increased the activity score of colitis, neutrophil infiltration in the colon and the expression of IL-1β, as well as the myeloperoxidase activity of colonic tissue in ghrelin-treated colitis mice compared with saline-treated colitis mice." (PMID 35050153, 2022). "In the development of colitis, macrophages secrete inflammatory cytokines such as IL-1β and IL-12, leading to inflammatory cell aggregation, increasing inflammatory cytokine secretion, and promoting Th cell differentiation, thereby exacerbating immune response." (PMID 35784693, 2022). "Elevated IL-1β mediates anxiety-like behavior in this model of experimental colitis." (PMID 35379260, 2022). "In the case of the IL-1β gene expression, we found that anethole at doses of 31.25 (P < 0.001), 125 (P < 0.001), and 250 mg/kg (P < 0.01) considerably decreased the expression of IL-1β in comparison to the colitis (saline-treated) group." (PMID 35432569, 2022). "Furthermore, in two mouse models of colitis-associated CRC, PINK1 disruption increased TNFα, IL-1β, IL-6, and IFN-β mRNA expression, and increased colon tumorigenesis, suggesting a role for PINK1 as a tumor inhibitor in CRC." (PMID 36499214, 2022). "IFN-γ, IL-1β, and IL-6 also play a crucial role in the development of colitis." (PMID 35992694, 2022). "Additionally, the correlation of the expression of pro-inflammatory cytokines, such as IL-1β and TNF-α with colon inflammation caused by Clostridium sensu stricto 1, has been observed." (PMID 36432504, 2022). "It showed that the level of IL-1β and TNF-α was also increased in colitis-associated cancer." (PMID 36016583, 2022). "It is confirmed that Prevotella aggravates the colitis via meditating the maturity of IL-1β." (PMID 36389768, 2022). "Mice with induced colitis were subjected to forced moderate exercise, which led to an increase in cytokines such as Tnf, Il1b, and Il10 in the colon and exacerbated colitis symptoms, whereas 30 days of VWR attenuated colitis in these mice and was associated with a decrease in Tnf." (PMID 35159375, 2022). "In the same model, the mRNA expression and protein production of NFATc4 increased, while TNF-α and IL-1β expressions (both mRNA and protein) were downregulated by this treatment, thereby preventing weight loss caused by TNBS-induced colitis and improving macroscopic and microscopic scores." (PMID 36235004, 2022). "Interestingly, potential mechanistic insight into the intestinal epithelial injury from IL-1β has been recently demonstrated through single cell RNA sequencing of intestinal tissue, from both humans and mice with colitis." (PMID 36203564, 2022). "Moreover, distinct Candida albicans species were enriched in the intestinal mucosa of UC patients and exacerbated colitis via induction of IL-1β and secretion of candidalysin, which triggers a Th17 response." (PMID 36232412, 2022). "On the other hand, the animal group treated with curcumin nanostructured microemulsion had a significant reduction in the tissue levels of TNF-α (170.5 ± 5.01 pg/mL), as well as IL-1β and IL-6, compared to the colitis treated with NS, and to the COL/MES group rats." (PMID 35976279, 2022). "Furthermore, sulfasalazine and hFm alleviated cGm-induced colitis: they suppressed myeloperoxidase activity, IL-1β and IL-6 expression and increased IL-10 expression." (PMID 35631220, 2022). "Additionally, we found that colitis is associated with meaningfully increase in gene expression of inflammatory cytokines including TLR4, TNF-α and IL-1β." (PMID 35432569, 2022). "Drugs block the NLRP3 pathway, reduce IL-1β production, and attenuate colitis." (PMID 36590401, 2022). "IL-1β could promote the macrophages and monocytes to secrete a variety of pro-inflammatory cytokines, it played an key role in the pathogenesis of colitis." (PMID 35572623, 2022).
colitis (continued). "Pathogenic bacteria of colitis such as Shigella, Oscillospira and Xenorhabdus, which were negatively correlated with most SCFAs, were significantly positively correlated with MPO, TNF-α, IL-1β, IL-6, IL-17, and IgE (P ≤ 0.05)." (PMID 36451737, 2022). "Previous studies demonstrated that Uro-A reduced colon inflammation and improved intestinal barrier integrity in DSS-induced mouse models of colitis by reducing the cytokines interleukin 1 beta (IL-1β), interleukin 6 (IL-6), and tumor necrosis factor alpha (TNFα)." (PMID 35645801, 2022). "In a colitis experimental model of colitis, vitexin significantly inhibited the TNF-α, IL-6, and IL-1β expression, suggesting that this compound may suppress the inflammatory response to improve colitis-induced liver damage." (PMID 35164352, 2022). "Overall, higher production of IL-6 and IL-1β in MCJ-deficient mice could indicate a higher presence of protective T cells, and therefore, resistance to colitis." (PMID 35705557, 2022). "FMT was shown to decrease IL-1β production in a mouse model of colitis." (PMID 35783298, 2022). "Odoribacter could stimulate the production of IL‐6 and IL‐1β and the expansion of Th17 cells to confer resistance to colitis and colon cancer." (PMID 36348804, 2022). "Oxymatrine treatment has a significant regulatory effect on apoptosis by blocking the TLR-9/MyD88/NF-κB pathway associated with downstream TNF-α, IL-1β, and IL-6 protein expression levels, restoring TJ protein expression and attenuating TNBS-induced colitis symptoms." (PMID 35873579, 2022). "Disturbance of intestinal immune regulation is an essential factor in the pathogenesis of IBD, in which proinflammatory cytokines TNF-α, IL-6, IL-1β and anti-inflammatory cytokine IL-10 are the key indicators reflecting the degree of inflammation in the model of colitis." (PMID 36615796, 2022). "The small RNAs contained in ginger ELNs had protective effects against DSS-induced colitis by reducing the levels of pro-inflammatory cytokines, such as IL-1β and TNF-α, and by promoting the expression of interleukin 22 (IL-22) through I3A, which activates the aryl hydrocarbon receptor pathway." (PMID 34065193, 2021). "Given together, these results indicate that IL-1β-primed ERCs could exhibit therapeutic effects in relieving histopathological damages in DSS-induced colitis." (PMID 34090510, 2021). "Thus, we conclude that Schisandrin B suppressed NLRP3 inflammasome activation-mediated IL-1β level and pyroptosis in intestinal epithelial cells of colitis model by the activation of AMPK/Nrf2 dependent signaling- ROS-induced mitochondrial damage." (PMID 34628369, 2021). "However, oral gavage and intraperitoneal injection of buspirone alleviated IS-induced colitis: it suppressed myeloperoxidase activity, IL-1β, IL-6, and TNF-α expression, and NF-κB+/CD11c+ cell population in the colon." (PMID 33731795, 2021). "Similarly, NLRP3 is protective in the oxazolone model of colitis, and disease severity can be ameliorated by exogenous administration of IL1β or IL1862." (PMID 34075172, 2021). "Also in this study, it was shown that cytokines produced by Th1 (i.e., TNF-α, IFN-γ) and Th17 cells (i.e., IL-17) or promoting Th17 cell differentiation (IL-1β, IL-6) were significantly increased in T cell transfer colitis mice compared to control mice." (PMID 34248633, 2021). "CHOP may aggravate colitis through macrophage infiltration, production of reactive oxygen species (ROS) and IL-1β, and aggravation of intestinal mucosal cell apoptosis." (PMID 34659400, 2021). "Thus, NAM had anti-inflammatory activity in mice with DSS-induced colitis by inhibiting the proinflammatory cytokines IL-6, IL-12p70, IL-1β, and TNF-α." (PMID 33748287, 2021). "Tnf-α, Il-1β, Il-6, and iNOS are crucial in the pathogenesis of colitis." (PMID 33777833, 2021).